CXCL12 (C-X-C motif chemokine ligand 12)
Description:
Chemoattractant active on T-lymphocytes and monocytes but not neutrophils. Activates the C-X-C chemokine receptor CXCR4 to induce a rapid and transient rise in the level of intracellular calcium ions and chemotaxis. Also binds to atypical chemokine receptor ACKR3, which activates the beta-arrestin pathway and acts as a scavenger receptor for CXCL12/SDF-1. Binds to the allosteric site (site 2) of integrins and activates integrins ITGAV:ITGB3, ITGA4:ITGB1 and ITGA5:ITGB1 in a CXCR4-independent manner. Acts as a positive regulator of monocyte migration and a negative regulator of monocyte adhesion via the LYN kinase. Stimulates migration of monocytes and T-lymphocytes through its receptors, CXCR4 and ACKR3, and decreases monocyte adherence to surfaces coated with ICAM-1, a ligand for beta-2 integrins. CXCR4 signaling axis inhibits beta-2 integrin LFA-1 mediated adhesion of monocytes to ICAM-1 through LYN kinase. Inhibits CXCR4-mediated infection by T-cell line-adapted HIV-1. Plays a protective role after myocardial infarction. Induces down-regulation and internalization of ACKR3 expressed in various cells. Has several critical functions during embryonic development; required for B-cell lymphopoiesis, myelopoiesis in bone marrow and heart ventricular septum formation (By similarity). Stimulates the proliferation of bone marrow-derived B-cell progenitors in the presence of IL7 as well as growth of stromal cell-dependent pre-B-cells (By similarity). [SDF-1-beta(3-72)]: Shows a reduced chemotactic activity. [SDF-1-alpha(3-67)]: Shows a reduced chemotactic activity. Binding to cell surface proteoglycans seems to inhibit formation of SDF-1-alpha(3-67) and thus to preserve activity on local sites.
Synonyms: IRH; PBSF; SDF1; SCYB12; SDF-1a; SDF-1b; TLSF-a; TLSF-b; TPAR1; TLSF; formerly SDF1A; SDF1B
Tractability: Small molecule: a structure with a bound ligand is known; a high-quality ligand is known. Antibody: its Gene Ontology location is reachable by antibodies, with high confidence; UniProt places it where antibodies can reach, with medium confidence; UniProt predicts a signal peptide or a membrane-spanning region. PROTAC: a small molecule that binds it is known. Other modalities: a drug acting on it is in phase 2 or 3 trials.
Target class: Secreted protein
Gene: Protein-coding gene on chromosome 10 (44,370,165 to 44,386,493, reverse strand). Ensembl gene ENSG00000107562.
Subcellular location: Secreted
Pathways (Reactome):
Signal Transduction: Chemokine receptors bind chemokines; Estrogen-dependent gene expression; G alpha (i) signalling events; Nuclear signaling by ERBB4
Developmental Biology: Signaling by ROBO receptors
Gene Ontology:
Molecular function: chemokine activity; chemokine receptor binding; CXCR chemokine receptor binding; integrin binding; protein binding; signaling receptor binding
Biological process: cell chemotaxis; cellular response to chemokine; chemokine (C-X-C motif) ligand 12 signaling pathway; chemokine-mediated signaling pathway; CXCL12-activated CXCR4 signaling pathway; integrin activation; negative regulation of dendritic cell apoptotic process; negative regulation of intrinsic apoptotic signaling pathway in response to DNA damage; negative regulation of leukocyte tethering or rolling; positive regulation of cell adhesion; positive regulation of monocyte chemotaxis; positive regulation of T cell migration; positive regulation of vasculature development; axon guidance; blood circulation; cell adhesion; chemotaxis; G protein-coupled receptor signaling pathway; immune response; induction of positive chemotaxis; intracellular calcium ion homeostasis; positive regulation of calcium ion import; positive regulation of cell migration; regulation of actin polymerization or depolymerization; response to virus; and 19 more
Cellular component: extracellular exosome; extracellular matrix; extracellular region; membrane; external side of plasma membrane
Genetic constraint (gnomAD): Loss-of-function variants: 4 observed, 8.57 expected, observed/expected ratio (o/e) 0.47, 90% interval 0.23 to 1.07. That is too few expected variants to judge how well the gene tolerates losing a copy. Missense variants: 118 observed, 103.12 expected, observed/expected ratio (o/e) 1.14, 90% interval 0.99 to 1.33. Synonymous variants: 53 observed, 42.03 expected, observed/expected ratio (o/e) 1.26, 90% interval 1.01 to 1.59.
Homologues: Orthologues: chimpanzee CXCL12 (99% identical), macaque CXCL12 (97% identical), guinea pig CXCL12 (94% identical), dog CXCL12 (93% identical), mouse Cxcl12 (93% identical), rat Cxcl12 (92% identical), pig CXCL12 (91% identical), tropical clawed frog cxcl12 (66% identical), zebrafish cxcl12b (47% identical), zebrafish cxcl12a (45% identical).
Diseases named in the same sentence as CXCL12 in open-access papers:
CXCL12 is named in the same sentence as 656 diseases in open-access papers, as found by Europe PMC text mining. Sharing a sentence is not in itself a finding about the gene and the disease. The quoted sentences say what the papers report.
breast carcinoma (740 papers, 2002 to 2026). "In human breast cancer cell lines, AQP3 peroxiporin activity was found to be implicated in CXCL12/CXCR4-dependent breast cancer cell migration." (PMID 39941100, 2025). "In this context, our study provides a new insight: the co-expression of high levels of cytokeratin and CXCL12 is associated with better prognosis in breast cancer patients." (PMID 40182181, 2025). "With regard to the relationships between CXCL12 SNPs and breast cancer, we additionally discovered that rs1144471 and rs3740085 were associated with susceptibility to breast cancer in the Chinese population, particularly in postmenopausal individuals." (PMID 39703847, 2024). "Further analyses of CXCL12 associated with breast cancer subtypes revealed that the homozygous mutation AA genotype in SNP rs1144471 was associated with ER-negative and PR-negative breast cancer but not with HER-2-positive breast cancer." (PMID 39703847, 2024). "The interaction between the CXCL12 SNPs and the association with breast cancer survival further suggest potential targets for better detection and treatment opportunities for breast cancer." (PMID 39703847, 2024). "Organs with high CXCL12 expression are associated with some sites of metastatic breast cancer, such as the lung, bones and lymph nodes." (PMID 39605887, 2024). "A recent study demonstrated that the polymorphism rs1801157 on the CXCL12 gene was associated with breast cancer and estrogen receptor positivity in Chinese." (PMID 39703847, 2024). "CCL2 and CXCL12 SNPs are associated with breast cancer susceptibility in overweight and postmenopausal women, and the effect varies according to subtypes." (PMID 39703847, 2024). "The CXCL12 SNP rs3740085 was associated with breast cancer in the additive model (OR=1.15, 95%CI=1.01-1.32), particularly in postmenopausal women." (PMID 39703847, 2024). "The interaction of SNPs within CXCL12 gene and the association with breast cancer survival further suggest potential targets for improved risk assessment and treatment strategies." (PMID 39703847, 2024). "The SNP rs1144471 located in CXCL12 showed a significant association with ER-, and PR- breast cancer, with OR of 0.43 (95% CI=0.23-0.84) and 0.38 (95% CI=0.19-0.74) for the recessive model, respectively." (PMID 39703847, 2024). "The association between plasma CCL2 and CXCL12 with breast cancer was further examined in 72 patients and 75 controls." (PMID 39703847, 2024). "GMDR analysis further suggested that the interaction of rs1801157 and rs3740085 in CXCL12 gene was significantly associated with susceptibility to breast cancer." (PMID 39703847, 2024). "Association of CCL2 and CXCL12 gene SNPs with lymph node metastasis and histological grade of breast cancer." (PMID 39703847, 2024). "In conclusion, the present study highlights that the CCL2 and CXCL12 SNPs are linked to breast cancer susceptibility, especially in overweight and postmenopausal Chinese women." (PMID 39703847, 2024). "The interaction between rs1801157 and rs3740085 in CXCL12 SNPs was statistically significant, and rs3740085 was also associated with breast cancer survival." (PMID 39703847, 2024). "The association between single nucleotide polymorphisms (SNPs) in the CCL2 and CXCL12 genes and the susceptibility to breast cancer was investigated using logistic regression models." (PMID 39703847, 2024). "We therefore added the analysis of plasma CCL2 and CXCL12 which confirmed the association with breast cancer." (PMID 39703847, 2024). "It was showed that the risk score was significantly higher in the stage III and IV patients, implying this CXCL12-related risk score correlated to the progression of breast cancer." (PMID 37564657, 2023). "Univariate and multivariate Cox analyses revealed that age, tumor stage, metastasis stage and the CXCL12-related risk score were independent prognostic factors for breast cancer patients." (PMID 37564657, 2023).
breast carcinoma (continued). "Here, we report that DPP-4 deficiency promotes breast cancer cell survival via the induction of autophagy by the C-X-C motif chemokine 12 (CXCL12)/C-X-C receptor 4 (CXCR4)/mammalian target of rapamycin (mTOR)/hypoxia inducible factor (HIF)-1α axis." (PMID 37760498, 2023). "In this study, we systematically investigated the association between the expression of CXCL12 and clinical characteristics in breast cancer, and found that CXCL12 was lower expressed in the tumor tissues and linked with a survival advantage." (PMID 37564657, 2023). "Cell adhesion molecules such as ICAM, B1 integrin, P-selectin, PECAM-1, CXCL12 and SDF-1 have also been proposed as part of the mechanisms underlying breast carcinoma metastases." (PMID 36497364, 2022). "The present study was aimed to assess the relationships between CXCL12 polymorphisms (rs1801157, rs2297630, and rs2839693) and susceptibility and clinicopathological features of breast cancer." (PMID 35079936, 2022). "Previous studies suggested that CXCL12 was involved in the development, metastasis, and invasion of breast cancer, and genetic variants were associated with the diagnosis and prognosis of patients with breast cancer." (PMID 35079936, 2022). "The relationships between CXCL12 polymorphisms and clinicopathological factors of breast cancer were also evaluated." (PMID 35079936, 2022). "In this study, we evaluated the association between three CXCL12 polymorphisms (rs1801157, rs2297630 and rs2839693) with breast cancer." (PMID 35079936, 2022). "CCL2 and CXCL12 produced by breast cancer-associated fibroblasts and tumor cells promote the recruitment and differentiation of monocytes into immunosuppressive TAMs." (PMID 35309358, 2022). "In a study of chemokine CXC motif ligand 12 (CXCL12), a prognosis factor similar to IDO1, a high CXCL12 expression was associated with a shorter OS in esophagogastric, pancreatic, or lung cancer, while the opposite was the case for breast cancer." (PMID 36212460, 2022). "In breast cancer, the overexpression of miR-222 inhibits the chemotaxis of tumor-associated macrophages by targeting C-X-C motif chemokine ligand 12 (CXCL12)." (PMID 36428980, 2022). "A statistical association was found between CXCL12 rs1801157 polymorphism and breast cancer risk, possibility of metastasis, and estrogen receptor status." (PMID 35079936, 2022). "CXCL12 expression and activated hepatic stellate cells (aHSCs) abundance were associated with breast cancer patients with liver metastases, the interplay between NK cells and aHSCs master switched breast cancer dormancy to outgrowth." (PMID 35980268, 2022). "CXCL12/CXCR4-dependent cell migration is a critical process in breast cancer progression; however, its underlying mechanism remains to be elucidated." (PMID 35847914, 2022). "The CAF-secreted chemokine, CXCL12, has been directly implicated in the tumorigenic progression of carcinomas, including breast cancer." (PMID 36118583, 2022). "We found a positive relationship between CXCL12 rs1801157 polymorphism and breast cancer susceptibility." (PMID 35079936, 2022). "Binding to endothelium by adhesion molecules such as ICAM, B1 integrin, P-selectin, PECAM-1, CXCL12 and SDF-1 have also been proposed as part of the mechanisms underlying breast carcinoma metastases." (PMID 36497364, 2022). "Previous studies showed a positive association between CXCL12 G801A polymorphism and breast cancer risk." (PMID 35079936, 2022). "CXCL12 overexpression induces EMT in breast cancer cells, activating stem cell-associated genes like SOX2, OCT4, and NANOG, promoting a stem-like phenotype marked by ALDH1 expression and Wnt/β-catenin pathway activation." (PMID 33530455, 2021). "CXCL12 downregulates the expression of Kiss1 in breast cancer cells, a gene associated with metastasis inhibition." (PMID 33096815, 2020). "High CXCL12 expression in patients with basal-like breast cancer was associated with poor prognosis and high accumulation of Tregs in tumors." (PMID 33096815, 2020).
breast carcinoma (continued). "Binding of CXCL12 to its receptor CXCR4 on breast cancer cells is able to promote tumor cell proliferation and high levels of CXCL12 are associated with poor prognosis." (PMID 33006013, 2020). "Distinct signaling proteins such as heat shock factor 1 (HSF1), TGF-β and CXCL12 have been implicated in transformation of stromal cells in breast cancer." (PMID 33096815, 2020). "Diverse mechanisms underlying the CXCL12/CXCR4-induced therapy resistance have been reported in breast cancer." (PMID 33096815, 2020). "In breast cancer, the CXCL12/CXCR4 axis is implicated in the homing of cancer cells to metastatic sites." (PMID 32079335, 2020). "The CXCR4/CXCL12 pathway in M2 perivascular TAMs has been implicated in breast cancer relapse after chemotherapy in preclinical models." (PMID 33096815, 2020). "In female breast cancer, the cytoplasmic expression of CXCL12 was associated with better disease-free survival and OS." (PMID 32188473, 2020). "It has been established that the chemokine, stromal-derived factor-1 (SDF-1 or CXCL12), is implicated in homing of tumour cells to bone, where metastatic breast cancer cells, for example, express its receptor CXCR4." (PMID 31713180, 2019). "Strikingly, in MDA-MB-231 breast cancer cells, the loss of mdig appeared to favor the open chromatin structure of the genome for metastatic genes CXCL12, CXCR4, MMP-1, and MMP-9, while enhancing the formation of closed chromatin for UPA." (PMID 30254753, 2018). "This study is reporting for the first time on CXCL12 rs1801157 single nucleotide polymorphism (SNP) in breast cancer (BC) patients in the Pakistani population." (PMID 28929029, 2017). "One of the major mechanisms underlying the chemotactic attraction of breast cancer cells towards bone has been identified in the CXCR-4/CXCL-12 axis, also critical for other bone-metastasizing tumors, such as prostate cancer." (PMID 27571063, 2016). "For example, cancer-associated fibroblasts (CAF) stimulate the growth of breast cancer cells through secretion of CXCL12." (PMID 27136535, 2016). "Previous reports suggested that engagement of CXCR4 by CXCL12 causes the activation of FAK that contributes to CXCL12-dependant chemotaxis in breast cancer cells." (PMID 26993780, 2016). "Reportedly, CXCR7 modulates CXCR4 signaling and enhances CXCL12-induced cell migration and metastasis of breast cancer cells, and LCP1 is implicated in the CXCL12-induced migration of chronic lymphocytic leukemia cells." (PMID 26413813, 2015). "Macrophage chemokines that are regulated by HA, including CXCL2 and CXCL12, have similarly been implicated in breast cancer progression and have been shown to promote migration and invasion of these cancer cells." (PMID 26106384, 2015). "In breast cancer, CXCL12 is secreted by both carcinoma-associated fibroblasts and cancer cells in the primary tumor environment and is constitutively expressed in common sites of metastasis, such as bone, lung, and liver." (PMID 25909600, 2015). "A recent study showed that CXCL12 is involved in breast carcinoma-associated fibroblast differentiation into myofibroblasts during tumor progression." (PMID 25121739, 2014). "Recently, it has been reported that CXCL12 concentration in blood plasma exhibits a strong association with the risk of distant metastasis of breast cancer cells and patient survival." (PMID 25237365, 2014). "In this study, we investigated CXCR4 and CXCL12 expression in breast cancer and analyzed its association with clinicopathological factors by immunohistochemistry first." (PMID 24810923, 2014). "A previous report demonstrated that CXCL12 induced breast carcinoma-associated fibroblast differentiation into myofibroblasts." (PMID 25121739, 2014). "Association of CCL2 and CXCL12 gene SNPs with breast cancer susceptibility." (PMID 39703847, 2024).